CDK3 (cyclin dependent kinase 3)
Diseases named in the same sentence as CDK3 in open-access papers (continued):
Sharing a sentence is not in itself a finding about the gene and the disease.
metastatic cancer (1 paper, 2016). A carcinoma which has spread from the original site of growth to another anatomic site. "Further, we detected Cdk3 activity in normal colorectal tissue, primary and metastatic cancer using in vitro kinase assay." (PMID 26755651, 2016). "Cdk3 protein expression was significantly increased in metastatic cancer compared to primary cancer (P < 0.05)." (PMID 26755651, 2016). "The results showed that Cdk3 scores were stronger in metastatic cancer than that in primary cancer, and primary cancer being stronger than in normal colorectal tissues." (PMID 26755651, 2016). "The results showed that Cdk3 activity is the highest in metastatic cancer tissues, and being higher in metastatic cancer than that in primary one (P < 0.05)." (PMID 26755651, 2016). "Cdk3 was found to highly express in metastatic cancer and induce cell motility and invasion." (PMID 26755651, 2016).
metastatic colorectal cancer (1 paper, 2016). "In the present study, we found that Cdk3 is highly expressed in metastatic colorectal cancer." (PMID 26755651, 2016).
metastatic tumors (1 paper, 2016). "And the third one is that EMT marker alternation existed in Cdk3-mediated metastatic tumor ex vivo." (PMID 26755651, 2016).
osteosarcoma (1 paper, 2021). A usually aggressive malignant bone-forming mesenchymal neoplasm, predominantly affecting adolescents and young adults. "RFC4, CDK3, CDC45 and NCAPG were found to be associated with osteosarcoma for the first time in our analysis, and thus could be novel diagnostic/prognostic biomarkers or treatment targets." (PMID 34156352, 2021).
renal carcinoma (1 paper, 2022). A carcinoma arising from the epithelium of the renal parenchyma or the renal pelvis. "We performed overall survival analyses and found that CDK3 was the only one in above seven candidate genes significantly associated with prognosis of renal cancer patients." (PMID 35927229, 2022). "SLC27A2 small interfering RNA was used to transfect renal cancer cells and down-regulate CDK3 expression in mRNA and protein." (PMID 35927229, 2022). "We also verified the regulatory effect of SLC27A2 on CDK3 using qRT-PCR and western blot in two renal cancer cells." (PMID 35927229, 2022). "As a result, we speculated that SLC27A2 might take part in the migration and invasion of renal cancer cell by coordinating CDK3-mediated EMT in ccRCC." (PMID 35927229, 2022). "The mRNA expression of CDK3 in renal cancer tissues was much higher than in normal tissues, consistent with the survival analysis results, indicating that CDK3 was an unfavorable biomarkers for RCC and might participate in cancer progression." (PMID 35927229, 2022). "We hypothesized that CDK3 could also affect EMT processes in renal cancer." (PMID 35927229, 2022).
cancer (20 papers, 2008 to 2025). A tumor composed of atypical neoplastic, often pleomorphic cells that invade other tissues. "The results show that in almost all cancer cell lines tested, including the cell lines described in S5 Table, genetic loss of CDK3 and CDK5 has a minimal impact on cell viability." (PMID 32645016, 2020). "More importantly, Cdk3 highly expresses in various cancer, and its expression is associated with the degree of infiltration, lymph node metastasis and clinical staging." (PMID 26755651, 2016). "The expression of CDK3 is deficient in normal tissue but overexpressed in many cancers." (PMID 37102261, 2023). "Despite the limited literature on CDK3’s role in cancer compared to other cell cycle-related CDKs, emerging studies have unveiled intriguing functions." (PMID 39800748, 2025). "In this cancer, SLC27A2 influences EMT transition by negatively regulating CDK3, whose low expression is associated with a poor prognosis." (PMID 41373732, 2025). "We also confirmed the cancer‐promoting function of CDK3 through proliferation and migration‐related experiments." (PMID 37102261, 2023). "By referring to related literatures and databases, E2F1, GLI1, CDK3, and Mcm4, as candidate target genes, were found to be closely related to the occurrence of cancers, which was very helpful to clarify the mechanism of EZH2 in PC." (PMID 37198697, 2023). "Among the seven ERGs in our constructed prognostic signature, CDK3 is the most influential cancer‐promoting gene." (PMID 37102261, 2023). "Our data provides miR-873/CDK3 axis is a potential target to treat ER positive cancer especially tamoxifen resistant subtype, but how to target this axis is a challenge." (PMID 31120927, 2019). "In these studies, CYP4Z2P and CYP4Z1 were also found to act as ceRNAs for CDK3 (cyclin dependent kinase 3) and hTERT (human telomerase reverse transcriptase) through miR-125a in sub-ceRNA networks that further potentiate cancer development." (PMID 29702599, 2018). "According to the present literatures, the major function of CDK3 is a promoter for cancer cell growth and transformation by phosphorylating its substrates, such as ATF1, c-Jun, NFAT3 and IK3-1/Cables." (PMID 29156693, 2017). "Cdk3 is involved in cancer progression, but very little is known about its mechanism in cancer development and progression." (PMID 26755651, 2016). "The second is that Cdk3 activated AP-1 through induction of c-Jun Ser 63/73 phosphorylation, AP-1 activation promoted cancer cell from epithelial to mesenchymal transition." (PMID 26755651, 2016). "Cdk3 is overexpressed in a number of cancer tissues and cancer cell lines, and it has been found to be deregulated or mutated in numerous human tumors." (PMID 26755651, 2016). "These genes are key players in cell cycle regulation and cancer, including CDK3 and COL7A1." (PMID 39193365, 2024). "We used qRT-PCR to validate the increment of CDK3 in ccRCC cells and cancer tissues." (PMID 35927229, 2022). "CDK3 has been linked to EMT and the growth of cancerous tumors." (PMID 35927229, 2022). "The anti-cancer agent norcantharidin (NCTD) has been found to regulate miR-873/CDK3 axis." (PMID 36266723, 2022). "Although several researchers discovered that CDK3 related to cell growth in some kinds of cancer, the functions of CDK3 during tumor development remains unclear." (PMID 29156693, 2017). "Recently, Cdk3 was found a novel function, which is involved in cancer development and progression." (PMID 26755651, 2016). "To confirm whether Cdk3-activating AP-1 exists in cancer metastasis, we co-transfected pHis6-tagged c-Jun (His-c-Jun) and pRcCMV-HA-Cdk3 (HA-Cdk3) into HEK 293 cells." (PMID 26755651, 2016). "We think that Cdk3 is involved in not only cancer development but also metastasis." (PMID 26755651, 2016). "However, the reported findings on CDK3 in cancer are inconsistent." (PMID 35814446, 2022).
cancer (continued). "Furthermore, CDK3 expression may be regulated by certain miRNAs in a variety of different cancers, including miR-873, miR-125a-3p and miR-150." (PMID 33504681, 2021). "Based on these, we speculated that Cdk3 may be involved in cancer metastasis." (PMID 26755651, 2016). "Next step is to investigate whether Cdk3 increases the motility and invasion of cancer cell." (PMID 26755651, 2016). "According to these findings, the CDK3 level was considerably higher in RCC cells and cancer tissues." (PMID 35927229, 2022). "To determine the potential contribution of inhibiting CDK3 and CDK5, as compared to CDK2 and CDK9, we analyzed data publicly available from genome-wide CRISPR-Cas9 screens in >700 cancer cell lines (from the Cancer Dependency Map project)." (PMID 32645016, 2020). "Experimental overexpression of miR-214 in HCC cells leads to suppression of E2F2, CDK3, and CDK6, cell-cycle arrest at the G1–S checkpoint, and disrupted proliferation of the cancer cells." (PMID 26498144, 2016). "The protein level of CDK3 was higher in non-malignant cancer cell lines (MCF7, T47D), compared with malignant cancer cell lines (MDA-MB-231, BT549)." (PMID 29156693, 2017).
tumor (19 papers, 2016 to 2025). "In clinical samples of nasopharyngeal carcinoma, up-regulation of CDK3 has been associated with tumor infiltration, lymph node metastasis and TNM staging." (PMID 36266723, 2022). "Clinical investigations showed that Cdk3 highly expresses in various tumor, and its expression was associated with the degree of infiltration, lymph node metastasis and clinical staging." (PMID 26755651, 2016). "Mechanistic and functional studies revealed that SLC27A2 orchestrates EMT through CDK3, partially reversing this process and inhibiting tumor progression." (PMID 35927229, 2022). "These regions contained tumor-related genes, such as Muc16, Pik3, and Bcl2 in amplification regions and Hras, Notch1, Apc2, Ccnd1, Batf2, Dapk3, Smarca4, Traf2, Traf3, Cdk3, and Cdh4 in deletion regions." (PMID 36424557, 2022). "Instead, comparable levels between tumours and normal mammary glands were found for Cdk3, Cdk5, and Cdk6." (PMID 34646365, 2021). "We also found that NCTD inhibits cell proliferation and tumor growth and miR-873/CDK3 axis mediates cell proliferation suppression of NCTD." (PMID 31120927, 2019). "It is very likely that E2F2, CDK6, and CDK3 act cooperatively to initiate or promote tumor development and progression." (PMID 26498144, 2016). "However, little research about the possible mechanisms between CDK3 and immunity has been reported, and further exploration of the mechanisms of CDK3 affecting tumor immunity and invasiveness is needed." (PMID 37102261, 2023). "In summary, SLC27A2 expression is diminished in ccRCC, and this lower SLC27A2 expression may accelerate tumor progression through CDK3-mediated EMT." (PMID 35927229, 2022). "Thus, we assume that CDK3 could exhibit different roles in different tumor stages and tumor types, and further experiments need to be performed to verify this hypothesis." (PMID 29156693, 2017). "When phosphorylated by CDK3/cyclin-C, RB1 is a major regulator of cell division and works as a tumor suppressor, promoting the G0-G1 transition." (PMID 36531719, 2022). "Immunohistochemistry and Western blot also consistently showed that the expression of E2F2, CDK3, and CDK6 in miR-214-overexpressing cell-line tumor models were lower than those in the vector-control tumors." (PMID 26498144, 2016). "The current study has demonstrated that miR-214 is a new tumor-suppressive miRNA in HCC that targets multiple cell-cycle stimulated gene (E2F2, CDK3, and CDK6) promoters." (PMID 26498144, 2016). "Our results demonstrate that miR-214 has tumor-suppressive activity in HCC through inhibition of E2F2, CDK3 and CDK6." (PMID 26498144, 2016). "In addition, CDK3 and DPH1, which have been reported to inhibit or have the potential to inhibit tumor development, was observed to be markedly negatively correlated with risk scores." (PMID 34090418, 2021). "As a mediator of cell cycle, CDK3 indeed participate in several tumor cell growth, however, we should not constrain its function only in cell cycle." (PMID 29156693, 2017). "Furthermore, our animal experiments and studies using clinical samples showed an inverse correlation between miR-214 levels and expression of E2F2, CDK3, and CDK6, as well as tumor progression." (PMID 26498144, 2016). "It did not mention if CDK3 exerts the similar role in ER-negative tumor cells." (PMID 29156693, 2017). "The opposing relationships between CDK2/CDK3 (negative) and CDK5 (positive) with regulatory T cell populations suggest that selective CDK inhibition could serve dual therapeutic functions—blocking tumour proliferation while simultaneously enhancing anti‐tumour immunity." (PMID 40682474, 2025).
CDK3 also shares sentences with these, for which no sentence is quoted: gastric cancer (2 papers); glioblastoma (2); liver cancer (2); nasopharyngeal carcinoma (2); pancreatic cancer (2); ACTHomas (1); acute myeloid leukemia (1); brain tumor (1); cardiomyopathy (1); cervical cancer (1); COVID-19 (1); esophageal squamous cell carcinoma (1); head and neck squamous cell carcinoma (1); hematologic malignancies (1); leukemia (1); periodontitis (1); renal cell carcinoma (1); rheumatoid arthritis (1); schizophrenia (1); stomach cancers (1).